CEACAM22P (CEA cell adhesion molecule 22, pseudogene)
Gene: Transcribed unprocessed pseudogene on chromosome 19 (44,542,798 to 44,549,166, reverse strand). Ensembl gene ENSG00000230666.
Diseases named in the same sentence as CEACAM22P in open-access papers:
CEACAM22P is named in the same sentence as 2 diseases in open-access papers, as found by Europe PMC text mining. Sharing a sentence is not in itself a finding about the gene and the disease. The quoted sentences say what the papers report.
diabetic neuropathy (1 paper, 2025). A chronic, pathological complication associated with diabetes mellitus, where nerve damages are incurred due to diabetic microvascular injury involving small blood vessels that supply these nerves, resulting in peripheral and/or autonomic nerve dysfunction. "In addition, further research is needed to explore the roles of specific biomolecules implicated in diabetic neuropathy development, such as SLC30A1, TRBJ2‐7, OLFM1, TCF7L2, MCF2L, CEP295NL, CEACAM22P, TSHZ2, and PDZD4." (PMID 40692573, 2025).
CEACAM22P also shares sentences with these, for which no sentence is quoted: tumor (1 paper).